HIF1A (hypoxia inducible factor 1 subunit alpha)
Diseases named in the same sentence as HIF1A in open-access papers (continued):
Sharing a sentence is not in itself a finding about the gene and the disease.
glioma (continued). "In comparison to HIF-1α, HIF-2α may be a specifically attractive target in GBMs, as it is expressed in glioma stem cells but not normal neuronal progenitors and it is activated by long-term hypoxia, in addition to its association with poor patient survival." (PMID 33842321, 2021). "Indeed, we observed significant negative correlations between ClockLoss and HIF-1A targets (CA9, VEGFA and LDHA) in glioma." (PMID 31014368, 2019). "However, in the glioma specimens, as the level of HIF-1α expression increased, we observed a corresponding increase in the number of POSTN+ cells in non-stem glioma cells (NSGCs) (CD133-)." (PMID 27602954, 2016). "In severe hypoxic conditions, both HIF-1α and HIF-2α resulted upregulated in GSCs while in mild hypoxia only HIF-1α is upregulated in glioma stem cells and in nonstem cells and in neural stem cells (NSCs), whereas HIF-2α is predominantly expressed only in GSCs." (PMID 26880981, 2016). "Similarly, we did not observe a rise in HRE reporter gene activity or in expression of the HIF-1α target genes GLUT1, VEGF and MCT4 (and data not shown) in any of the five glioma cell lines examined." (PMID 21791085, 2011).
lung carcinoma (476 papers, 2004 to 2026). "ISO decreases the NEDD9 protein levels, causing the downregulation of HIF-1α and reduction in β-Catenin activation, leading to the inhibition of the malignancy of human lung cancer cells." (PMID 40362444, 2025). "This inhibition reduces the proliferation, migration, invasion, and angiogenesis of lung cancer cells associated with HIF-1α." (PMID 40860815, 2025). "HIF-1α expression was associated with tumor proliferation, resistance to apoptosis, and increased mortality in patients with lung cancer, which indicates its potential prognostic significance." (PMID 40427193, 2025). "High tumor levels of HIF-1α have previously been shown to be associated with apoptosis and higher survival rates among lung cancer patients." (PMID 39856383, 2025). "The hypoxia-induced increase in HIF-1α in lung cancer cells also causes a decrease in Claudin-5 expression, which increases the permeability of the blood–brain barrier, promoting lung cancer metastases to the brain." (PMID 40507913, 2025). "While VHL mutation is crucial for constitutive HIF-1α activation in lung cancer, understanding how cancer cells activate HIF-1α in VHL wild-type cancers is a key research focus." (PMID 40691138, 2025). "Further studies revealed that the tumor-promoting effect of PDLIM2 downregulation in lung cancer involves the accumulation of ROS, succinate, and the associated activation of HIF-1α." (PMID 38880883, 2024). "Strikingly, inflammation-associated COX2 activation is also known to enhance HIF-1α activity in some tumor models such as breast and lung cancer." (PMID 38612478, 2024). "NARFL knockdown caused drug resistance via HIF-1α pathway, which wound drive cell survival in lung cancer patients treated with Cisplatin." (PMID 37821486, 2023). "Currently, it has been reported that the high expression of HIF-1α remains a major cause of recurrence after radiofrequency ablation for lung cancer." (PMID 37948404, 2023). "Under hypoxic condition, HIF-1α was highly expressed in cancer-associated fibroblasts in human lung cancer tissues and spontaneous lung tumors in mice." (PMID 36986550, 2023). "Hypoxia-inducible factor (HIF-1α) is a therapeutic target in lung cancer, and the deacetylase sirtuin 3 (SIRT3) is closely associated with tumorigenesis." (PMID 37747648, 2023). "HIF proteins, especially HIF-1 alpha (HIF-1α), are closely associated with lung cancer occurrence, metastasis, and angiogenesis." (PMID 35918758, 2022). "Intriguingly, the concordant expression of STIL with SLUG displayed an especially high correlation in patients with metastatic lymph nodes (R = 0.76), suggesting that there is a strong association of the HIF1α-STIL-SLUG axis in lung cancer specimens." (PMID 35365182, 2022). "The HIF-1α expression level was closely associated with occurrence, growth, angiogenesis, local infiltration and distal metastasis of lung cancers." (PMID 36559162, 2022). "The KRAS-pathway is known to be involved in cellular proliferation associated with colon, pancreatic, and lung cancer and has previously been shown to have an influence on HIF1A translational regulation within hypoxia." (PMID 35326510, 2022). "HIF-1α SNP rs11549465 was associated with overall cancer risk including lung cancer risk, in a meta-analysis based on 26 383 patients, equally distributed between controls and cases." (PMID 34298636, 2021). "A recent meta-analysis showed that HIF-1α rs11549465 and rs11549467 polymorphisms increased the lung cancer risk in Asian populations." (PMID 33621198, 2021). "A significant association between MMP-9 and HIF-1α expression was reported in studies of lung cancers." (PMID 35280249, 2021). "In the present paper, a part of the underlying mechanism in lung cancer was explained from the axis of miR-449a/KDM3A/HIF-1α." (PMID 34044859, 2021). "Kaplan–Meier plots demonstrate that the high levels of HK2, SLC2A1 (GLUT1), LDHA, and HIF1a expression were associated with poor survival of lung cancer patients." (PMID 34692483, 2021).
lung carcinoma (continued). "More importantly, survival analysis indicated that the high expression of HIF-1α was associated with a poor survival in patients with lung cancer." (PMID 33154192, 2020). "A positive correlation between HIF1A and CD68 in colon cancer patients was identified but, unexpectedly, in cases with higher macrophage infiltration, HIF1A expression was associated with a better prognosis, in contrast to breast, gastric, and lung cancers." (PMID 32231135, 2020). "The HIF-1α expression was already studied in vitro and in vivo in lung cancer and it is associated with poor prognosis." (PMID 31903166, 2019). "In xenograft models of different human cancers, such as hepatoma, cervical carcinoma, and lung cancer, YC-1 significantly inhibited tumor growth and prolonged the survival periods, associating with reduced HIF-1α expression and blocked angiogenesis." (PMID 30634531, 2019). "miR-210 is up-regulated by EGCG in lung cancer cells which is associated with HIF-1α (hypoxia-inducible factor 1-alpha)." (PMID 31781485, 2019). "Our gain and loss of function studies support a key role for HIF-1α in the promotion of lung cancer by COPD-like inflammation." (PMID 30250643, 2018). "Hypoxia inducible factor-1α (HIF-1α) is associated with the progression and metastasis of lung cancer." (PMID 28302216, 2017). "There are, however, few studies on the relationship between the single nucleotide polymorphisms of HIF-1α and susceptibility to lung cancer." (PMID 28302216, 2017). "A SNP in the let-7 miRNA binding site in the 3′UTR of KRAS is associated with risk of lung cancer development and HIF1A c.*191T>C SNP in the 3′ UTR of the gene is significantly correlated with rectal cancer risk." (PMID 26872370, 2016). "In this study, we determined the mechanism underlying the ability of Daxx to suppress hypoxia-induced lung cancer metastasis, showing that Daxx acts through the HIF-1α/HDAC1/Slug pathway." (PMID 28004751, 2016). "The expression levels of UCHL1 correlate with those of HIF-1α and are strongly associated with the poor prognosis of breast and lung cancer patients." (PMID 25615526, 2015). "Recent association studies between miRNA markers and lung cancer development have demonstrated that the miRNAs miR-18, miR-199, and miR-519c can suppress HIF-1α expression for the purpose of assessing cancer prognosis." (PMID 26528854, 2015). "Our meta-analysis suggests that the substitution of G allele with A of HIF-1α gene G1790A polymorphism is a risk factor of cancer, especially for pancreatic cancer, lung cancer, renal cell carcinoma and head and neck cancer." (PMID 24808762, 2014). "Our meta-analysis suggests that the substitution of G with A of HIF-1α gene G1790A polymorphism is a risk factor of cancer, especially for pancreatic cancer, lung cancer, renal cell carcinoma and head and neck cancer." (PMID 24808762, 2014). "HIF-1α expression is also associated with poor prognosis and resistance to radiation therapy in lung cancer, colon cancer, and cervical cancer." (PMID 26555969, 2013). "We reported previously that mtDNA mutations that induce complex I defects in mouse lung carcinoma cells can increase the metastatic potential via ROS overproduction and resultant overexpression of Hif1α and Mcl-1." (PMID 21853128, 2011). "The hypoxic conditions inside tumors often cause HIF-1α to be increased in lung cancer." (PMID 40205002, 2025). "Thus, LUBAC plays a causal role in promoting HIF1α expression and angiogenesis through catalyzing HIF1α linear ubiquitination in lung cancer." (PMID 38272870, 2024). "Some studies have suggested that HIF-1α may be prognostic in lung cancer, as it could be associated with tumor aggression and related to chemo-resistance." (PMID 37445752, 2023). "Demethyleneberberine caused G1 arrest of lung cancer cells by down-regulating c-Myc/HIF1A." (PMID 36139919, 2022). "In addition, higher mRNA expression of Hif1a was associated with poorer survival in lung cancer patients." (PMID 36531060, 2022).
lung carcinoma (continued). "Indeed, there is evidence that expression levels of HIF1A by tumor cells have a diagnostic and prognostic significance among different histological types of lung cancer." (PMID 36551790, 2022). "Moreover, cigarette smoke extract, which is a prevalent risk factor for COPD and lung cancer, also elevates HIF-1α in a concentration-dependent manner." (PMID 36338690, 2022). "Thus, overexpression of HIF-1α has a strong correlation with high metastatic risk, poor prognosis, pathological types and grade, and the survival of patients with lung cancer." (PMID 36359829, 2022). "Elevated HIF-1α levels have also been associated with lung cancer development and progression." (PMID 33621198, 2021). "As the overexpressed HIF-1α can result in the occurrence, angiogenesis, invasion, and metastasis of lung cancer, we hypothesized that COVID-19 infection might promote lung cancer development via HIF-1α-associated pathways." (PMID 34277453, 2021). "In conclusion, the increased presence of ANGPTL4 due to HIF-1α accumulation that is caused by nickel in lung cells may be one mechanism by which nickel exposure contributes to lung cancer progression." (PMID 31963541, 2020). "Additionally, this research group indicated that miR-18a potentially increases radiosensitivity by targeting ataxia telangiectasia mutated (ATM) and hypoxia-inducible factor 1 alpha (HIF-1α) in lung cancer cells and CD133+ stem cells." (PMID 31873828, 2019). "To test whether COPD-like lung inflammation, and HIF-1 activation are linked causatively to lung cancer promotion, we studied the role of the HIF-1α pathway using genetic targeting of this pathway in airway epithelial cells in mice in vivo." (PMID 30250643, 2018). "Besides this, heat treatment can cause hypoxia in the local tissue and increase HIF-1a expression levels, which can induce the over-proliferation of any residual tumors, leading to the recurrence of lung cancer." (PMID 27456341, 2016). "Therefore, it would be informative to validate additional genetic factors, including miRNAs, that are involved in modulating HIF-1α level in collaboration with mesenchymal markers to potentially help predict risk of aggressive lung cancer." (PMID 26528854, 2015). "Moreover, high expression levels of both UCHL1 and HIF-1α (+++ and ++) were strongly associated with the poor overall survival of lung cancer patients." (PMID 25615526, 2015). "Moreover, expression levels of UCHL1 in breast and lung cancers were found to be associated with those of HIF-1α and poor prognosis in cancer patients." (PMID 25615526, 2015). "In the subgroup analysis according to cancer type, the results suggested that the HIF-1α G1790A polymorphism significantly increased the risk of lung cancer, renal cancer, oral cancer and pancreatic cancer, but the CI for the oral cancer subgroup was very wide." (PMID 25496056, 2014). "Furthermore, HIF1α is implicated in mechanisms such as DNA repair, contributing to chemo- and radio-resistance across various tumors, including glioblastoma, hepatocarcinoma, and lung cancer." (PMID 39697237, 2024). "Taken together, these results highlight the strong involvement of COPD-derived hypoxia in inducing the release of EVs by endothelial cells and the potential role of HIF-1α within EVs in fostering lung cancer development that may be exploited as biomarker of lung cancer risk." (PMID 37838700, 2023). "In addition, we also analyzed the mutation frequency of the HIF1α gene in different types of tumors, and the results showed that the mutation frequency of head and neck cancer (12.5%), lung cancer (10.53%), and pancreatic cancer (10.06%) ranked the top three, respectively." (PMID 35860430, 2022).
lung carcinoma (continued). "However, previous studies demonstrated that HIF-1α was closely related to the cell proliferation and invasion abilities of lung cancer cells, which was associated with the regulation of ERK1/2 pathway, and ERK1/2 phosphorylation increased HIF-1α protein expression 51-53." (PMID 32792865, 2020). "In order to study the causal role of HIF-1α in lung cancer promotion, we have targeted its expression in the airway epithelium of the CC-LR mouse by crossing this mouse to a conditional knock out mouse with both alleles of exon 2 of Hif1a flanked by loxP sites." (PMID 30250643, 2018). "HIF-1α rs2057482 may be associated with lung cancer susceptibility." (PMID 28302216, 2017). "HIF-1α stabilization and downstream target expression were investigated in mouse lung carcinoma epithelial (CMT167) cells and isolated mouse and human PASMCs under different hypoxic conditions." (PMID 41810557, 2026). "Prior studies have shown LCA exhibits anti‐cancer effects in various contexts, including suppressing PD‐L1 in lung cancer inhibiting HIF‐1α and respiration in colon cancer." (PMID 41163796, 2025). "Previous research has demonstrated that CEBPD promotes lymphangiogenesis and metastasis in lung cancer by regulating the HIF-1α/VEGF-C signaling pathway." (PMID 40895068, 2025). "It was found that their proliferation rate was still significantly lower than that of lung cancer cell lines after 48 hours of upregulation of MIF or HIF-1α, and the proliferation rate of MIF+AT2 was higher than that of DMOG and closer to tumor cells." (PMID 41210694, 2025). "In conclusion, this study elucidates the therapeutic potential of YFJDT to modulate EMT and angiogenic mimicry in lung cancer by promoting ferroptosis through HIF1A." (PMID 39912781, 2025). "In summary, HSP70, via HIF-1α SUMOylation, inhibited ferroptosis, inducing lung cancer recurrence after RFA." (PMID 40313865, 2025). "Nicotine engages with the α5-nAChR on the surface of lung cancer cells, activating the Akt signaling pathways, upregulating HIF-1α signaling, and increasing VEGF, thereby accelerating the growth of lung cancer." (PMID 40143965, 2025). "Crucially, lactate stabilizes HIF‐1α and induces H3K18la, thereby promoting M2‐like gene expression and driving lung cancer progression." (PMID 41190507, 2025). "The inhibitory effects of ACE2 on MMP-9 and HIF-1α in lung cancer align with results from several previous studies." (PMID 41303321, 2025). "WDR72 has been recognized as a prognostic biomarker in non-small cell lung cancer, where it modulates the AKT/HIF-1α signaling pathway, contributing to enhanced lung cancer stemness." (PMID 41332473, 2025). "Gold–silver alloy nanoparticles (Au–Ag NPs) have been utilized in the treatment of colorectal and lung cancers, where they influence HIF-1α expression and promote autophagy." (PMID 40004215, 2025). "Here, we demonstrate that ERCC6L plays a critical role in promoting lung cancer stemness by stabilizing HIF-1α expression." (PMID 40691138, 2025). "A hypoxic lung cancer-secreted exosomal miRNA, miR-23a has the potential to upregulate HIF-1α in endothelial cells, thereby increasing angiogenesis, as well as vascular permeability, in cancer cells through the inhibition of tight junction protein, ZO-1." (PMID 40507913, 2025). "In lung cancer, HIF-1α is upregulated in response to hypoxia and regulates or is regulated by ncRNA transcription, promoting angiogenesis and the related growing tumour, and facilitating the metastatic process." (PMID 40869000, 2025). "The expression of HIF-1α is modulated by microRNA-29a, leading to the suppression of autophagy in lung cancer cells." (PMID 40004215, 2025). "Epigallocatechin gallate (EGCG), the primary catechin in green tea, has demonstrated the ability to diminish HIF-1α activity in lung cancer, both in vitro and in vivo." (PMID 40004215, 2025).